IL27 (interleukin 27)
Diseases named in the same sentence as IL27 in open-access papers (continued):
Sharing a sentence is not in itself a finding about the gene and the disease.
infection (211 papers, 2010 to 2026). The state of being infected such as from the introduction of a foreign agent such as serum, vaccine, antigenic substance or organism. "While all HSPCs showed preferential expression of the IL-27R, with LTHSCs and MPP2s exhibiting the highest, the loss of IL-27 during infection resulted in reduced HSPC fitness." (PMID 39868131, 2025). "While all HSPCs showed preferential expression of the IL-27R, with long-term hematopoietic stem cells (LTHSCs) and MPP2s exhibiting the highest, the loss of IL-27 during infection resulted in reduced HSPC fitness." (PMID 41396163, 2025). "Elevated levels of IL-27 cytokine during the neonatal period predispose neonatal mice to more severe infection." (PMID 40977737, 2025). "As one of the few cytokines that shows statistically significant changes in concentrations in the acute phase of the infection, IL-27 is directly linked to the markers of cell-mediated immunity." (PMID 39063193, 2024). "Analysis of spleen cells in the treated mice showed consistently higher PbT‐II proportions and counts at day 14–28 post‐infection comparable to IL‐27‐deficient mice." (PMID 37855243, 2023). "Among the cytokines, IL-27 was suggested to negatively control host immunity against A. fumigatus, which was evidenced by the decreased fungal colonization and less severe infection in IL-27 receptor-deficient mice." (PMID 36690696, 2023). "Malaria infection elicits both protective and pathogenic immune responses, and IL‐27 is a critical cytokine that regulate effector responses during infection." (PMID 37855243, 2023). "The signaling pathways associated with MDA-5 and interleukin-27 (IL-27) were also highly enriched during early infection." (PMID 37963152, 2023). "IL27 is mainly produced by APCs, upon infection caused by intracellular pathogens, and can promote innate and adaptive immunity." (PMID 35174107, 2022). "Studies involving cecal ligation and puncture (CLP)-induced bacterial sepsis and S. aureus pneumonia following influenza demonstrated that IL-27 mediates enhanced susceptibility to infection by attenuating Th17 immunity and promoting IL-10 induction." (PMID 36028492, 2022). "More recently the cytokine IL-27 has been implicated in regulation of the pulmonary immune response during infection." (PMID 32425944, 2020). "IL-27 is upregulated upon Pseudomonas aeruginosa infection in septic mice, increasing susceptibility to the infection and decreasing clearance of the pathogen." (PMID 33276561, 2020). "Severe infection in C5ar1−/− mice was associated with diminished serum concentrations of IL-12, IL-27, and IFN-γ." (PMID 32733463, 2020). "Our study represents a novel approach to understanding bacterial dissemination in a neonatal model relative to the host response, and drives home a direct association between IL-27 and severity of infection." (PMID 31818960, 2020). "In contrast, the gene encoding the other subunit of IL-27, Il27a, displayed a dynamic behavior with expression induced upon infection in some BM monocytes with a further increase of frequency in the spleen and the SILP." (PMID 31872076, 2019). "Exploratory analyses were subsequently conducted as a means to understand the failure of IL-27 as a diagnostic biomarker for infection in the a priori analysis." (PMID 30475852, 2018). "As a potent anti-inflammatory cytokine, IL-10 also inhibits IL-27 production during infection-associated inflammation." (PMID 29021521, 2017). "In vivo findings revealed that mice deficient for Ebi3, a subunit of IL-27, were extremely susceptible to infection with 103 trypomastigote forms of T. cruzi, a quantity that was not lethal to WT mice." (PMID 29033934, 2017). "More importantly, we provided direct evidence, that infection-associated IL-27 signaling served to extend the survival of the infected host by dampening CD4+ T cell activation and their secretion of IFN-γ." (PMID 26222157, 2015).
infection (continued). "Thus, during infection the loss of IL-27 signaling enhances the skewing of HSPCs ex vivo toward monocyte differentiation." (PMID 39868131, 2025). "The results indicate that IL-27 plays a crucial role in regulating immunopathology, and that administering IL-27 at appropriate times could be an effective treatment for severe inflammation caused by infections." (PMID 39063193, 2024). "In addition, during the late stages of the infection, IL-27 along with IL-10 is considered to limit tissue damage caused by L. braziliensis." (PMID 35090305, 2022). "Thus, deficiency of IL-27 signaling promoted intrahepatic accumulation of Ly6C+ monocytes and their differentiation to moDCs and Tip-DCs during infection with African trypanosomes." (PMID 33593983, 2021). "However, increased levels of IL-27 shortly after birth are also associated with detrimental effects during infection." (PMID 32802395, 2020). "However, this improved infection outcome is in contrast to other studies that demonstrate elimination of IL-27 results in marked susceptibility to infection from Trypanosoma cruzi, Trichuris muris, Leishmania major, and Toxoplasma gondii." (PMID 31818960, 2020). "LDV infection resulted in a threefold increase in survival rate with reduced weight loss and liver inflammation but with the establishment of permanent chimerism that correlated with decreased interleukine (IL)‐27 and interferon (IFN)γ plasma levels." (PMID 28474504, 2017). "Here we show that following infection with SeV, IL-27 deficiency leads to increased lung pathology and disease severity as well as to higher frequencies of eosinophils and alternatively activated macrophages (AAMs), consistent with an increased bias towards a type 2 immune response." (PMID 28129374, 2017). "However, IL-27 impairs control of acute mouse hepatitis replication and associated pathology following infection of the CNS and this phenotype is associated with reduced accumulation of IL-10+ CD4+ T cells." (PMID 27926930, 2016). "We detected elevated IL-27 plasma levels in European patients with active visceral disease caused by Leishmania infantum, which returned to basal levels after successful treatment, suggesting this cytokine as a probable infection mediator." (PMID 27867384, 2016). "Consistent with this, WSX-1/IL-27 was recently demonstrated to have a critical role in limiting the effector CD4+ T-cell-mediated immunopathology caused by IL-12-dependent IFN-γ production during infection with lethal P. berghei NK65." (PMID 26991425, 2016). "Though IL-27, along with IL-10, has been shown to enhance nasal colonization and increase susceptibility to S. aureus pneumonia, its role in suppressing inflammation in the later stages of infection may be beneficial in CC024 mice." (PMID 39178306, 2024). "To explore whether IL-27 signalling was associated with changes in CD4+ T cell metabolism during infection, we first measured mitochondrial mass and membrane potential using MitoTracker dyes in WT and Il27ra-/- CD4+ T cells and Th1 cells 14 days after L. donovani infection." (PMID 33049000, 2020). "Cytokines utilizing the STAT3 signaling pathway including IL-6, IL-21, and IL-27 have been implicated in driving Tfh differentiation, but due to their partially compensatory pathways, separating the requirements for individual signals throughout infection has proved challenging." (PMID 25569154, 2015). "Cytokine profiling revealed an acute Th1-skewed response, with elevations in CXCL9, CXCL10, IL-27, IFNγ, IL-12, and IL-18 during early infection." (PMID 41636514, 2026). "Males had higher overall levels of pro-inflammatory cytokines and IL-10 and lower levels of IL-27, which are known to inhibit the protective responses to Salmonella infection." (PMID 41810958, 2026). "Neutrophil degranulation in response to infection was expected and likely contributes to inflammation and tissue damage, but IL-27 production from a cell engaged in such inflammatory activity was surprising." (PMID 40682363, 2025).
infection (continued). "Flow cytometry showed that IL-27 producers increased significantly in the liver with infection and were predominantly F4/80+ and CD11b+ with subpopulations that emerged expressing additional markers." (PMID 40682363, 2025). "Infection-induced monopoiesis gives rise to a population of IL-27+ monocytes in the bone marrow that can then act on HSPCs to limit further monocyte production." (PMID 39868131, 2025). "Together, these data indicate that at homeostasis and during infection IL-27 can support LTHSC populations but also temper the downstream processes that lead to monocyte production." (PMID 39868131, 2025). "This suggests that depending on the tissue, location within the tissue milieu, and additional signals during infection, heterogeneous subpopulations of IL-27 producers expand." (PMID 40682363, 2025). "The IL-2RA+ IL-27− macrophages expressed many heat shock proteins, indicating that these cells were responding to protein-folding induced stress during infection (Data set S1)." (PMID 39882906, 2025). "Briefly, TO cultures were pretreated with isotype control or IL-27-neutralizing antibodies prior to infection with Cambodian ZIKV." (PMID 40502752, 2025). "While the data sets presented above indicate a role for IL-27 in the regulation of HSPC differentiation, it was unclear if loss of IL-27 signals during infection would affect their functionality and fitness." (PMID 39868131, 2025). "Limiting IL-27 signaling in neonates has the potential to balance the immune response during infection with maximum bacterial clearance, minimal tissue damage and improved survival." (PMID 40977737, 2025). "We observed a range of IL-27 in the serum during infection; however, we also found that serum values correlated positively with the bacterial burden in the blood." (PMID 40682363, 2025). "Testing the impact of IL-27 on functionality and fitness of hematopoietic stem and progenitor cells (HSPCs) during infection." (PMID 41396163, 2025). "Single-cell sequencing of IL-27 producers in the liver demonstrated individual subpopulations and insight into the purpose these cells serve during infection." (PMID 40682363, 2025). "Surprisingly, given the dramatic increase in circulating IL-27 at 20 h following infection, the abundance of IL-27 producers amongst the total CD45+ population in all tissues examined was smaller than expected." (PMID 40682363, 2025). "We were able to identify tissues suspected of IL-27 production and characterize the cell populations that make IL-27 during infection, which can be further explored to address specific downstream effects of blocking IL-27." (PMID 40682363, 2025). "Together, this work provides previously undescribed insight into the details of IL-27 producers during early-life infection." (PMID 40682363, 2025). "The liver displayed the highest number of IL-27 producers at baseline, and this population expanded in both the liver and lung during infection." (PMID 40682363, 2025). "Together, these data identified specific populations of cells responsible for making IL-27 during infection and how those populations change along with transcriptomic differences that occur during infection." (PMID 40682363, 2025). "These ex vivo and in vivo approaches indicate that exposure of LTHSCs to IL-27 during infection results in a stable program that limits monocyte production." (PMID 39868131, 2025). "For example, during infection with an attenuated strain of Plasmodium berghei, IL-27 was required for the induction of a neutrophil response, and in vitro IL-27 blunted the ability of HSPCs to differentiate into the macrophage lineage." (PMID 39868131, 2025). "Of note, IL-27 concentrations were the lowest in the breakthrough infection mice at 3 DPC compared to all other groups, including mock-challenged controls, despite detectable viral titers at this time point." (PMID 41190814, 2025).
infection (continued). "Consistent with our previous reports, there was a significant increase in IL-27 serum levels that was observed during infection in comparison to control." (PMID 40682363, 2025). "There are also reports during other infections and models that show IL-27 can regulate neutrophil and monocyte development." (PMID 39868131, 2025). "IL-27 concentrations in the breakthrough infection mice were significantly lower than those of PBS-vaccinated mock-challenged controls at 3 DPC, and significantly lower than those of TIV-vaccinated mock-challenged controls at 28 DPC." (PMID 41190814, 2025). "We showed that IL-27 producers comprised a distinct population of cells that varied in expression of myeloid surface markers and unique subpopulations develop during infection." (PMID 40682363, 2025). "While statistical significance was not achieved, there was an increased frequency of major histocompatibility complex class II expression on IL-27 producers in the spleen during infection while the inverse relationship was found in the liver." (PMID 40682363, 2025). "(F) Monocyte progenitors (MPs) (CD3−, NK1.1−, B220−, CD117+, CD34+, CD16/32hi, Ly6C+, CD135−, CD115+; orange box) in the bone marrow of infected WT and Il27−/− mice throughout infection." (PMID 41396163, 2025). "Significantly higher levels of IL-27 were found in UCB of newborns from the infection group (p < 0.01), and IL-27 continued to show significantly higher levels in the infection group compared to those in the non-infection group (p < 0.01) at 24 h after birth." (PMID 40171168, 2025). "MDMs infected with HIV-1 virus showed robust spreading infection, whereas there was little replication in MDMs treated with IL-27 after HIV-1 virus infection." (PMID 38566992, 2024). "The cellular sources IL-27 have been mainly attributed to APCs, however, lung epithelial cells in vitro produce IL-27 after infection with influenza A through a COX-2-derived prostaglandin E2 (PGE2) mechanism." (PMID 38966644, 2024). "This creates a positive feedback loop between the IFN/IL-27 pathway and the PRRs system to amplify inflammatory and antiviral responses until the infection is controlled or resolved." (PMID 38720890, 2024). "We highlight important aspects of IL-27 expression regulation, the critical cell sources at different stages of the infection and their impact in cell mediated immunity." (PMID 38966644, 2024). "Where lack of IL-27 signaling during this stage of infection leads to higher viral titers compared with wild type animals." (PMID 38966644, 2024). "This further points to a primary suppressive role of IL-27 in response to infection or vaccination with live agents." (PMID 38390338, 2024). "To then gain insights into germinal center cytokine effects on EBV-infected primary B-cells, we treated cells at 7 days post-infection with vehicle control, IL-4, IL-15, IL-21, IL-27 or multiple combinations thereof." (PMID 38683861, 2024). "In contrast, IL-27 secreted by B cells was relevant at later phase of the infection and facilitated maintenance and function of virus-specific CD4 T cells as well as CD4 TFH function, which promoted humoral immunity and viral clearance." (PMID 38966644, 2024). "In contrast, in the setting of MCMV, expression of IL-27 and induction of IL-10 by Tr1-like cells contributed to viral persistence in the latent phase of the infection." (PMID 38966644, 2024). "mRNA IL-27p28 transcripts are increased in the lungs during infection and IL-27 signaling promoted the generation of IL-10 secreting virus-specific CD8 T cells." (PMID 38966644, 2024). "In contrast, when IL-27 was administered at early time point of the infection, 1–7 days p.i, disease worsened, albeit reducing immunopathology." (PMID 38966644, 2024). "The first time IL-27 was discovered, its role was reported as a cytokine that induces Th1 cells that are protective in infection processes." (PMID 38314317, 2024).
infection (continued). "IL-10 was significantly increased in CC061 mice after MRSA infection, while IL-1β, IL-4, IL-9, IL-18, IL-23, and IL-27 were significantly increased in CC024 mice after infection." (PMID 39178306, 2024). "Analysis of serum cytokines 8 weeks post-challenge of control and vaccinated mice indicated that infection by Mtb induced production of IL-27, in addition to inflammatory cytokines IL-17 and IFNγ." (PMID 38390338, 2024). "This follows trends previously observed of IL-27 unresponsive animals exhibiting an improved ability to control Mtb after infection." (PMID 38390338, 2024). "These immune cells are known to produce IL-10, particularly during the resolution phase of the infection, and also IL-6 and IL-27, which promote the maturation of Treg cells in the respiratory tract." (PMID 39595633, 2024). "Treatment of Pcc‐infected mice with antimalarial drug starting 6 days after infection prevented second wave of PbT‐II expansion induced under IL‐27 neutralizing condition." (PMID 37855243, 2023). "Rather, inhibition of IL‐27 during the initial 7 days of infection was critical, suggesting that IL‐27 inhibits the generation of memory precursor CD4+ T cells that were destined toward differentiation to Th1‐type." (PMID 37855243, 2023). "We found that IL-27 enhanced HIV-1 growth when added on the fourth day after infection as observed from a time course assay, contrasting with the HIV-1 inhibition when added to infected PBMCs 2 h after infection." (PMID 36602368, 2023). "In the spleen of Il‐27−/− mice, PbT‐II cells had consistently higher proportions and total counts on day 14–28 post infection." (PMID 37855243, 2023). "Like other authors, we initially found that IL-27 reduced HIV-1 replication by 60 to 70% when added to infected PBMCs immediately after infection." (PMID 36602368, 2023). "Neonates exhibit elevated levels of IL-27 in the spleen and blood at resting state relative to adults, and these levels continue to rise during infection peaking at 24 h." (PMID 36891292, 2023). "On day 7 after infection, majority of CD11ahiCD49dhi PbT‐II cells were Th1 type, while Tfh type cells were dominant in CD11ahiCD49dlo cells in both anti‐IL‐27 mAb‐ and IgG‐treated mice (Fig EV2A and C)." (PMID 37855243, 2023). "Inhibition of IL‐27 during acute infection allowed maintenance of higher levels of memory CD4+ T cells and antibody, contributing to better protection upon reinfection, which depended on persistence of the infection." (PMID 37855243, 2023). "IL-27 promotes PD-1/PD-L1 and IL-10 expression, and we found that it was upregulated in the monocyte population throughout the infection." (PMID 37920474, 2023). "IL-27 inhibited HIV-1 replication when added to cells 2 h after infection, promoting the prototypical BST-2/Tetherin-induced virion accumulation at the cell membrane of HIV-1-infected PBMCs." (PMID 36602368, 2023). "Altogether, our results show that IL-27 is able to inhibit HIV-1 production when added to PBMCs just after infection and that the innate restriction factor BST-2/Tetherin is a critical mediator of this anti-HIV-1 effect." (PMID 36602368, 2023). "We found that IL-27-induced MDMs resist infection with HIV-1, and demonstrated that the resistance was associated with the down-regulation of spectrin beta, non-erythrocytic 1 (SPTBN1) or the induction of autophagy." (PMID 37910521, 2023). "In this study, we sought to determine if IL-27 modulates Cyp27B1 and hCAP levels in response to infection with M. tuberculosis." (PMID 36863206, 2023). "To uncover the responding CD4+ T cell subsets at the transcriptional level, we performed single‐cell RNA‐seq (scRNA‐seq) and compared PbT‐II cells from anti‐IL‐27 mAb‐ and control IgG‐treated mice on day 7 and 28 after infection (5 and EV3)." (PMID 37855243, 2023). "BST-2/Tetherin contributes to the IL-27-induced suppression of HIV-1 production when this cytokine is added to infected cells 2 h after infection." (PMID 36602368, 2023).